CXCL13 (C-X-C motif chemokine ligand 13)
Diseases named in the same sentence as CXCL13 in open-access papers (continued):
Sharing a sentence is not in itself a finding about the gene and the disease.
breast cancer (continued). "We investigated the clinical significance of CD4, forkhead box P3 (FOXP3), and B cell attracting chemokine leukocyte chemoattractant-ligand (C-X-C motif) 13 (CXCL13) in early breast cancer." (PMID 29482642, 2018). "CXCL13-positive CD4+ Tfh cells are associated with a high frequency of peritumoral tertiary lymphoid structures and generally favorable outcome in breast cancer." (PMID 29482642, 2018). "Detailed studies of breast cancer tissue have also revealed a population of infiltrating CXCL13+ CD4+ T cells." (PMID 30190721, 2018). "Tfh cells expressing CXCL13 were recently found to convert Treg-mediated immune suppression to activation of adaptive antitumor humoral responses in breast cancer." (PMID 29482642, 2018). "Expression of the CXC chemokine 13 (CXCL13) has been reported in tumors and serum of breast cancer, non-small cell lung carcinoma, and hepatocellular carcinoma, but little is currently known about the expression of CXCL13 in ovarian cancer." (PMID 29051715, 2017). "Analysis of Grade1 and Grade3 tumors using GGMs helped identify CXCL13 in breast cancer as hub gene." (PMID 29297310, 2017). "In the context of breast cancer, chemokines have been implicated in promoting the malignant phenotype: CXCL3, CXCL12, CXCL13, CCL21 and CCL5 are associated with tumour progression and metastasis in breast cancer." (PMID 27335323, 2016). "This is the first to indicate the clinical relevance of CXCL13 to young breast cancer and represents a potential therapeutic target for young breast cancer." (PMID 25990390, 2015). "The clinical correlation analysis and linear regression analysis supported the potential significance of CXCL13 in young breast cancer." (PMID 25990390, 2015). "The results displayed that CXCL13 mRNA expression was significantly up-regulated in 63.2 % of breast cancer tissues (96 in 152, P = 0.045) and indeed increased in young patients’ tissues compared with older counterparts (P = 0.011)." (PMID 25990390, 2015). "We did observe that CXCL13 protein was expressed in young breast cancer in a higher level than that of their older counterparts (P = 0.015)." (PMID 25990390, 2015). "IHC staining of CXCL13 was next conducted in 48 paraffin sections randomly selected from formalin-fixed and routinely processed breast cancer tissues (n = 30, young women group; n = 18, older women group)." (PMID 25990390, 2015). "The impact of CXCL13/CXCR5 on various types of cancers including breast cancer has recently attracted much interest." (PMID 25990390, 2015). "CXCR3 and CXCL13 expression were also included because they have been shown to correlate with breast cancer prognosis." (PMID 25505134, 2015). "Unpublished work from our lab supports that CXCL13 has at least four ISRE sites within its promoter and that IRF5 binds to two of them, increasing CXCL13 transcript and protein levels in breast cancer." (PMID 24762633, 2014). "While CXCL13 in breast cancer has been the most extensively studied to date, the expression of other TLS-inducing chemokines has also been implicated in this disease." (PMID 24762633, 2014). "Most striking, however, is the high prognostic power of CXCL13 expression across breast cancer subtypes even in triple negative and Her2+ tumors." (PMID 24762633, 2014). "This study also illustrates the possibility that some HRneg/Tneg signature genes emerge as blood biomarkers since CXCL13 blood levels were found to be specifically increased in patients with breast cancer." (PMID 20946665, 2010). "In this study, microarray analyses revealed the overexpression of chemokine CXCL13 in breast cancer specimens." (PMID 18781150, 2008). "Marked overexpression of CXCL13 protein in breast cancer tissue was further confirmed performing a quantitative ELISA analysis with the same lysates of tumours and healthy controls." (PMID 18781150, 2008).
breast cancer (continued). "Examining the presence of CXCR5, which is the only known receptor for chemokine CXCL13, within breast cancer tissues, we detected only a comparably weak expression." (PMID 18781150, 2008). "We analysed six different breast cancer cell lines and found RNA and protein expressions of CXCL13 in all but one and CXCR5 expression in four of six cell lines." (PMID 18781150, 2008). "To confirm our findings obtained by the RT–PCR array, we applied a CXCL13-specific real-time PCR to a larger set of samples from 34 breast cancer patients comprising all stages of disease." (PMID 18781150, 2008). "In addition, the Tfh-derived gene signature together with CXCL13 expression has been shown as a TLS marker in breast cancer." (PMID 40319321, 2025). "Although Tfh cells have been reported to produce CXCL13 in various cancer types, in breast cancer, so-called TfhX13 cells (Tfh-like cells that express CXCL13 and PD-1 but are negative for CXCR5) are associated with TLS formation." (PMID 37788648, 2024). "Existing studies have confirmed the indispensable role of CXCL13 in ovarian cancer and can act as a biomarker, but it remains unclear in other gynecologic tumors and breast cancer." (PMID 38459390, 2024). "Anti-CXCL13 antibodies have been used to stop tumor growth in breast cancer (BC)." (PMID 38333212, 2024). "CXCL13 promotes MDA-MB-231 cell apoptosis by CXCL13-CXCR5-ERK signaling pathway in breast cancer." (PMID 38459390, 2024). "In addition, CXCL13 promotes breast cancer progression by promoting the differentiation of B cells into regulatory B cells." (PMID 39834939, 2024). "Interestingly, these TFH cells were found as residents of peritumoral lymphoid structures (TLS) in breast cancer and characterized by CXCL13 expression." (PMID 39001456, 2024). "CXCL13 is involved in tumor immunity, though it exhibits duality in breast cancer." (PMID 38459390, 2024). "Besides CXCL13 producing CD8+ T cells tumour infiltrating CD4+ T cells also display an enhanced capacity for CXCL13 production in lung cancer, breast cancer and ovarian cancer." (PMID 37520560, 2023). "CX3CL1 and CXCL13 were shown to play an important role in the brain extravasation of breast cancer, while the following cytokines/chemokines were involved in the extravasation of melanoma cells (9IL-23, CXCL10, CXCR3, CXCL10 receptor, CCR4, CCL17, and CCR4) and lung cancer cells (TNF-α and CX3CR1)." (PMID 37190188, 2023). "In breast cancer tissues, CXCL13 gene was overexpressed at mRNA level and protein level." (PMID 37219794, 2023). "A breast cancer study reported that the overexpression of CXCL13 in both sera and breast tumor tissues implied that CXCL13 might play a role in breast cancer initiation and progression." (PMID 37686617, 2023). "Similarly, CXCL13 has been identified as a prognostic marker in various cancers, such as breast cancer, colorectal cancer, and clear cell renal cell carcinoma." (PMID 36798787, 2023). "In two other studies, CXCL13 expression was associated with higher tumor grade (grades 2–3), positive nodes, ER-negative status, longer metastasis-free survival, and a stronger prognostic effect in HER2-positive breast cancer." (PMID 37835488, 2023). "Moreover, the studies had shown that CXCL13 drives an anti-tumor immune response to limit tumor progression in mouse breast cancer cells." (PMID 38075694, 2023). "High CXCL9 and CXCL13 levels conferred an improved prognosis in early breast cancer." (PMID 35468838, 2022). "Nrf2 downregulates CXCL13, which suppresses breast cancer proliferation." (PMID 35571115, 2022). "Additionally, several previous investigations have demonstrated that CXCL13 is involved in the EMT process of breast cancer cells and clear cell renal cell carcinoma cells." (PMID 36613500, 2022). "It has been demonstrated that CXCL13 plays an important role in immune cell recruitment and adaptive immune response, suggesting that it may play multiple roles in young breast cancer patients." (PMID 36467500, 2022).
breast cancer (continued). "Several previous studies have also revealed that CXCL13 suppresses lymphocyte apoptosis in the spleen of pigs after porcine circovirus type 2 infection, while CXCL13 inhibition induces the apoptosis of breast cancer cells through blocking the CXCR5/ERK pathway." (PMID 36613500, 2022). "Clinical correlations with CXCL13 were performed by investigating the disease-free survival (DFS) of 794 breast cancer patients, which revealed that CXCL13 expression was positively correlated with DFS in breast cancer, especially in the human epidermal growth factor 2 (HER2+) group." (PMID 35053457, 2022). "Functional follicular helper T cells (Tfh) oriented by T-helper 1 (Th1) cells can promote humoral and cytotoxic immune responses in human breast cancer, and the presence of CXCL13-producing Tfh cells in tertiary lymphoid structures (TLS) of breast tumors robustly predicts positive clinical outcomes." (PMID 36189269, 2022). "CXCL13 suppresses lymphocyte apoptosis in the spleen of pigs after porcine circovirus type 2 infection, while CXCL13 inhibition induces the apoptosis of breast cancer cells." (PMID 36613500, 2022). "CXCL13-producing CD4+ Th cells have been reported in patients with breast cancer, in whom they were enriched in tertiary lymphoid structures, and their presence correlated with B cell infiltration and GC maturation at the tumor site and was associated with improved prognosis." (PMID 35439168, 2022). "According to the literature search results, higher CXCL13 expression was found in colorectal cancer, renal cell carcinoma, hepatocellular carcinoma, gastric cancer, breast cancer, lung cancer, pancreatic adenocarcinoma, cutaneous melanoma and leukemia, which were consistent with our study." (PMID 35141160, 2022). "One study showed that the CXCL13/CXCR5 axis was a good prognostic marker for breast cancer." (PMID 34947813, 2021). "Moreover, in a female BALB/c mouse model of breast cancer, an anti-CXCL13 antibody reduced tumor growth by impairing the CXCR5/Erk pathway and inducing tumor cell apoptosis." (PMID 34947813, 2021). "However, for early breast cancer, high CXCL13 content in a tumor is independently associated with favorable outcomes, supporting the importance of CXCL13 for humoral immune responses in anti‐breast cancer immunity." (PMID 33506656, 2021). "Furthermore, the intracellular CXCL13 were detected in human breast cancer cell lines MDA-MB-231, MDA-MB-468, and BT474 by flow cytometry, and all tumor cells had high expression levels of CXCL13." (PMID 35693216, 2021). "In addition, CXCL13 is involved in the progression of breast cancer cells through the CXCR5/ERK pathway." (PMID 34947813, 2021). "To date, CXCL13 has been widely accepted as an important mediator in the initiation, progression, and metastasis of solid tumors, and identified as one of the most strongly overexpressed chemokines in breast cancer." (PMID 35693216, 2021). "Additionally, in patients with HER2+ breast cancer increased CXCL13 correlated with better survival." (PMID 33193299, 2020). "Sera with elevated CX3CL1 and CXCL13 levels displayed barrier-compromising effects in vitro and therefore could contribute to the formation of brain metastases by breast cancer cells in vivo." (PMID 32321535, 2020). "In addition, CXCL13-treated breast cancer cells acquire a more elongated shape and a highly migratory phenotype characteristic of mesenchymal cells." (PMID 31354634, 2019). "Interestingly, a recent study showed that an anti-CXCL13 antibody reduces MDA-MB-231 breast cancer cell viability by promoting apoptosis." (PMID 31354634, 2019). "Analysis in breast cancer cell lines also revealed high levels of CXCL13 and expression of CXCR5." (PMID 31354634, 2019). "Indeed, IL21 producing Tfh cells are known to be associated with formation of tertiary lymphoid structures in human breast cancer patients in a CXCL13-dependent fashion." (PMID 31756235, 2019).
breast cancer (continued). "Moreover, CXCL13 was identified as the most strongly overexpressed chemokine in breast cancer tissue compared with normal breast tissue." (PMID 31354634, 2019). "Compared with healthy volunteers, the extremely high serum levels of MMP-9 and CCL21 in patients with colon cancer, of CCL11 in patients with gastric cancer, of CCL2/MCP-1 in patients with breast cancer and of CXCL13 in patients with liver cancer have been reported." (PMID 31754081, 2019). "In addition to the immune-related effects of CXCL13 in breast cancer, this chemokine exerts direct effects on breast cancer cells." (PMID 31354634, 2019). "In addition, CXCL13 is over-expressed in breast cancer and colon cancer patients and tightly related with the poor prognosis and overall survival of patients." (PMID 28881808, 2017). "CXCL13 may be a potential unfavorable factor for young breast cancer in Asia, though its prognostic value remains unclear." (PMID 25990390, 2015). "CXCL13 was shown to be able to induce an EMT in breast cancer via RANKL and Src activation." (PMID 26565418, 2015). "Our results were consistent with these previous reports, indicating a highly expressed CXCL13 in breast cancer though these data may be affected by the existence of fat tissue and adenocarcinoma cells in adjacent normal breast tissue." (PMID 25990390, 2015). "CXCL13 is overexpressed in breast cancer and mediates prostate cancer cell proliferation." (PMID 26565418, 2015). "In the present study, to validate the possible roles of CXCL13 in young breast cancer, we carried out multiple detections of CXCL13 expression at either mRNA or protein level in a relatively large set of clinical tissue specimens from patients with breast cancer." (PMID 25990390, 2015). "Among various chemokines, C-X-C motif ligand 13 (CXCL13, also named as B-cell attracting chemokine 1 (BCA-1)) is thought to play an important pro-tumor role in colon, prostate, and breast cancers through the interaction with its receptor, the C-X-C chemokine receptor 5 (CXCR5)." (PMID 25966773, 2015). "Collectively, these data indicated a high CXCL13 expression level in young breast cancer." (PMID 25990390, 2015). "Our finding of increased levels of soluble CXCL13 protein in the peripheral blood of breast cancer patients with advanced disease clearly suggests that this chemokine might be involved in the process of metastasisation." (PMID 18781150, 2008). "Breast cancer cells might interact through CXCR5/CXCL13 interactions to organise cellular cluster formation and compartmentalisation as has been shown for B cells in renal allografts and in salivary glands of patients with Sjogren's syndrome." (PMID 18781150, 2008). "Therefore, we performed extensive analyses of CXCL13 protein concentrations in the supernatant of breast cancer cell lines that had been cultured for 72 h under different conditions to find shed CXCL13." (PMID 18781150, 2008). "Our observation of a very low frequency of CXCL13-expressing leukocytes present within breast cancer tissue, however, would argue against the latter two hypotheses." (PMID 18781150, 2008). "In our view, the most perspicuous explanation for the increased presence of CXCL13 in breast cancer is that CXCR5/CXCL13 interactions might function in a similar way as they do in lymphatic tissue." (PMID 18781150, 2008). "Given the significant overexpression of CXCL13 at the mRNA and protein levels in breast cancer tumour samples, we sought to determine the expression patterns of the chemokine ligand and its receptor in human breast cancer cell lines." (PMID 18781150, 2008).
breast cancer (continued). "We show here for the first time that the ligand for CXCR5, CXCL13, is the most significantly overexpressed chemokine in breast cancer, supporting the idea of a role of CXCL13/CXCR5 interactions in promoting initiation and/or progression of this tumour type and, possibly, other human cancers." (PMID 18781150, 2008). "Not only in colorectal cancer (COAD), but TNFRSF18 and CXCL13 also have higher expression in tumour tissues across multiple tumour types, including breast cancer (BRCA) and stomach cancer (STAD), indicating that they may serve as a target for a broad range of cancers." (PMID 40770837, 2025). "Thus, CXCL12 and CXCL13/CXCR5 expression in the LNs of these breast cancer patients may be more relevant than other chemokines or receptors studied for LN involvement, resulting in a worse prognosis." (PMID 40584290, 2025). "Researchers went on to investigate 996 breast cancer patients receiving neoadjuvant chemotherapy and showed that CXCL13 expression was highly correlated with complete remission in HER2 patients, a finding that could help in the development of new immunotherapies." (PMID 38628669, 2024). "In vitro studies revealed that the chemokine (C-X-C motif) ligand CX3CL1 and CXCL13 levels were elevated in the serum of breast cancer patients with brain metastases, indicating that the presence of these chemokines may disrupt the integrity of the BBB and thus are implicated in the process of BM." (PMID 37190188, 2023). "However, the roles of CXCL13 in breast cancer development and progression remain controversial." (PMID 37958571, 2023). "However, another study suggested that CXCL13 may inhibit tumor growth in breast cancer through CXCR5/ERK signaling." (PMID 38075694, 2023). "Meta-analyses of transcriptomic data revealed that chemokine (C-X-C module) ligand 13 (CXCL13) within the CXCL9 module of the chemosensitive (pCR) model is one of the most robust predictors of favorable disease outcome for breast cancer patients treated with neoadjuvant chemotherapy." (PMID 35911770, 2022). "Finally, downregulated hub genes complement protein C3 and CXCL13 both could have implications in breast cancer progression and modulation in bone microenvironment." (PMID 34754042, 2021). "Similarly to our observation, particularly cerebrally metastasized breast cancer with meningeosis carcinomatosa may result in high CXCL13 CSF levels in up to 50% of cases, precluding a reliable differentiation from PCNSL on the basis of the CSF analysis alone." (PMID 33841320, 2021). "Moreover, flow cytometry and gene expression analysis of CD4+ T cell subsets revealed that highly infiltrated breast cancers also harbor TLS, and express markers such as Cxcl13, ICOS, IFNγ and TBX21/T-bet, commonly associated with follicular T helper (Tfh) and Th1 profiles." (PMID 34122434, 2021). "Therefore, we next asked the question whether soluble CXCL13 protein could be detected in the in vivo setting, given the high levels of protein expression within breast cancer tissue samples." (PMID 18781150, 2008). "For instance, B3GNT7 and CTSV predicted detrimental prognosis in BRCA2-mut breast cancers, and CD6, CXCL9, and CXCL13 predicted favorable outcomes in BRCA1-mut ovarian cancers." (PMID 40647506, 2025). "Using this strict approach, we selected two genes associated with a detrimental prognosis: B3GNT7 and CTSV in BRCA2-mut breast cancers, and three with a favorable prognosis: CD6, CXCL9, and CXCL13 in BRCA1-mut ovarian cancers." (PMID 40647506, 2025). "The results further confirmed that CXCL13 and MTDH can be used as independent prognostic factors of breast cancer to predict the survival of breast cancer patients." (PMID 38795164, 2024).